EPCAM (epithelial cell adhesion molecule)
Diseases named in the same sentence as EPCAM in open-access papers (continued):
Sharing a sentence is not in itself a finding about the gene and the disease.
cancer (continued). "Further, transcriptomics analysis confirmed overexpression of 3-MST (two-fold) in EpCAM+ cancer stem cells." (PMID 36978851, 2023). "Of note, differential promoter methylation of genes encoding for adhesion molecules, such as the epithelial cell adhesion molecule (Ep-CAM) and E-cadherin, has been frequently linked to cancer cell motility, and invasion and metastasis of cancer." (PMID 37880732, 2023). "Clinically, a Phase I study in patients with refractory solid tumors (including CRC and GC) reported a modest inhibitory effect of solitomab on the metastasis and progression of EpCAM + cancer." (PMID 38455361, 2023). "On the other hand, exosomal proteins, such as CD63, CD9, TSG101, and EpCAM, reflecting significant information about the cancer microenvironment, are highly enriched in exosomes derived from cancer cells." (PMID 38005527, 2023). "While regarded as the stem-like cancer cell, EpCAM-positive cells account for only 30% of HCC, thus making the CellSearch system unsuitable for CTCs detection in HCC." (PMID 36633681, 2023). "High expression of EpCAM has been observed on CSCs and targeting EpCAM is an effective strategy for cancer treatment." (PMID 37853413, 2023). "As for the biological mechanism, the isolation of CTCs is based on the antigen–antibody combination in which the common markers include EpCAM as a cancer stem cell marker, and HER2 and PSA as the targets for breast and prostate cancer, respectively." (PMID 36980712, 2023). "Even when EpCAM+ cells are detected, the exact cancer cell count can be hindered by the complexity of blood recovered from patients with widespread metastases." (PMID 37373781, 2023). "For solid tumors, catumaxomab (CD3xEpCAM BsAb) targeting epithelial cell adhesion molecule (EpCAM)-positive cancers showed benefit in reducing malignant ascites secondary to epithelial cancers, with an acceptable safety profile." (PMID 37569894, 2023). "Since most cancers are epithelial in nature, the most commonly used marker for CTCs is epithelial cell adhesion molecule (EpCAM), a “universal” marker of cancer." (PMID 37016296, 2023). "Most prior reports on CTCs in cancer are based on epitope capture using epithelial cell adhesion molecule (EpCAM) followed by immunostaining for cytokeratins (CK)." (PMID 36718027, 2023). "Designed ankyrin repeat protein (DARPin) Ec1 fused with the low immunogenic bacterial toxin LoPE provides specific and potent cytotoxicity against EpCAM-expressing cancer cells." (PMID 36769161, 2023). "As the advantageous effect of EPCAM on regulating self-renewal has previously been reported in various types of cancer cells, the potential role of EPCAM in regulating self-renewal in SiHa cells was confirmed in this study." (PMID 36674577, 2023). "EpCAM-CAR T-cells are now being tested in a number of clinical trials for several cancers such as breast cancer, HCC, pancreatic cancer, and GC, though their effectiveness has yet to be demonstrated (NCT02915445 and NCT05028933)." (PMID 37020537, 2023). "Our study showed that EPCAM was expressed in both pancreatic ductal cells and cancer cells; however, the expression intensity of cancer cells was higher than that of normal ductal cells, which was similar to the results of single cell sequencing." (PMID 37124494, 2023). "EpCAM expression varies between cancer types, and strong EpCAM expression can be used for CTC detection in some cancers." (PMID 36911396, 2023). "Epithelial cell adhesion molecule (EpCAM), a cancer stem cell biomarker, showed widespread expression in most normal epithelial cells and most cancers." (PMID 37664060, 2023). "We have also demonstrated that the thyroglobulin type-I domain of WT EpCAM binds and inhibits cathepsin-L protease, which hinders cancer cell invasion and lung metastasis." (PMID 37192201, 2023). "In line with our data, EpCAM expression assessed by flow cytometry was highly heterogenous, which was similarly reported in a cross-cancer IHC analysis." (PMID 37154925, 2023).
cancer (continued). "Several investigators have raised the potential prognostic significance of EpCAM overexpression in various cancers." (PMID 37627911, 2023). "The results of the profiling of the plasma samples showed exosomes from cancer patients had higher levels of EpCAM and CD24 expression in comparison to non‐cancer patients." (PMID 35898167, 2023). "EpCAM is expressed in many normal epithelial tissues and is also recognized as a biomarker of cancer stem cells." (PMID 36971124, 2023). "P16422|EPCAM and Q95604|1C17 from HCT116-specific group and Q9Y6N7|ROBO1 from DKO1-specific group are also high pathogenic cancer drivers (cancer driver score = 3)." (PMID 36639722, 2023). "They used this method to capture and release cancer cells that expressed the epithelial cell adhesion molecule (EpCAM)." (PMID 37388583, 2023). "Tissue microarray blocks of formalin-fixed and paraffin-embedded CRC tissues, with their non-cancer margins of resection, were sectioned and stained with EpCAM and E-cadherin primary antibodies." (PMID 37533952, 2023). "Consistent with the clonogenic assay results, DF5 decreased the CD133+EpCAM+ cancer stem-like cell subpopulation across all the PC cell lines." (PMID 36768301, 2023). "Comparison of EpCAM-ReTARGpp65 with the EpCAM-directed BiTE solitomab indicated a similar cancer cell elimination capacity but at ~55% decreased levels of T cell-secreted proinflammatory cytokines." (PMID 37568582, 2023). "An indirect method of modifying the surface of the QCR using protein A/G-mediated anti-EpCAM antibodies was developed to maximize the capture of cancer cells, which is a crucial factor in increasing the frequency shift." (PMID 37185508, 2023). "Analysis of epithelial cell adhesion molecule (EpCAM) expression indicated that both cancer cell lines expressed EpCAM." (PMID 38132919, 2023). "Here, the most used epithelial cell adhesion molecule (EpCAM) was selected as the representative biomarker, and the EpCAM-positive cancer cells were mainly studied." (PMID 37232858, 2023). "The epithelial cell adhesion molecule (EpCAM, CD326) is a multi-functional transmembrane glycoprotein overexpressed in normal epithelial cell and epithelial carcinomas such as cancers of pancreas, colon, stomach, lung, ovarian and so on." (PMID 36910604, 2023). "We selected the clinically relevant pan-carcinoma target antigen EpCAM for this purpose, as it is selectively overexpressed in 55%-75% of OC patients." (PMID 37509310, 2023). "For carcinomas, immunomagnetic antibodies directed against the epithelial cell adhesion molecule (EpCAM), an epithelial cell surface marker, have been used to target CTCs." (PMID 37446253, 2023). "The molecule of epithelial cell adhesion—EpCAM, is a transmembrane protein, described as a tumoral prognostic marker and an anchor for circulant tumoral cells highly expressed in carcinomas and their metastasis." (PMID 37754116, 2023). "In 1,375 pT2-4 carcinomas, the average EpCAM staining intensity was again intermediate (18.3 ± 12.3) and ranged between the values seen in pTa G2 low grade (p<0.001 for pTa G2 low grade vs. pT2-4) and pTa G3 tumors (p=0.071 for pTa G2 high grade vs. pT2-4)." (PMID 38282671, 2023). "In pT2-4 carcinomas, EpCAM staining was unrelated to grade (p=0.6), pT (p= 0.3), R-status (p=0.4) but significantly linked to pN (p=0.045) and L1 status (p<0.001)." (PMID 38282671, 2023). "The literature related that EpCAM expression occurs at a high level of primary carcinoma from the colon, stomach, prostate, lung, ovarian, and endometrial cancer." (PMID 37754116, 2023). "The epithelial cell-adhesion molecule (EpCAM) is hyperglycosylated in carcinoma tissue and the oncogenic function of EpCAM primarily depends on the degree of glycosylation." (PMID 37834237, 2023).
cancer (continued). "This approval was based on the results from the NCT00836654 trial, in which EpCAM-positive cancer patients were randomized to receive catumaxomab plus paracentesis (experimental group) or paracentesis alone (control group)." (PMID 36432631, 2022). "An important subpopulation of cancer cells is that of cancer stem cells (CSCs), which is characterized by the expression of specific markers, including epithelial cell adhesion molecule (EpCAM) and oval cell (OV6) protein." (PMID 35204240, 2022). "In many kinds of research, to make nanoparticles target CRC after systemic administration, a DNA EpCAM aptamer (SYL3C) having a strong affinity with EpCAM protein and cancer cells expressing EpCAM was modified on nanoparticles." (PMID 35566331, 2022). "In this review, we systematically summarize the pathological functions of EpCAM and its crosstalk with other signaling pathways in cancers, as well as its potential role in cancer diagnosis or prognosis." (PMID 36369033, 2022). "Catumaxomab (Removab) is the first bsAb-based T-cell engager that was approved by the EMA against CD3 and EpCAM for use in the treatment of malignant ascites in patients with EpCAM-positive cancer." (PMID 35628495, 2022). "One clinical trial has begun to evaluate the safety and efficacy of CAR-T cells that target EpCAM in patients with EpCAM-positive cancer (ClinicalTrials.gov Identifier: NCT03013712)." (PMID 35205714, 2022). "For example, epithelial cell adhesion molecule (EpCAM) genes within the GO: 0098742 were considered the marker of HCC cancer stem cells for a long time." (PMID 36482487, 2022). "Currently, one trial (NCT03013712) being conducted to evaluate safety and efficacy of EpCAM targeting CAR T-cells in the treatment of patients with EpCAM positive cancer, including prostate, plans to enclose 60 participants." (PMID 36428811, 2022). "This is a significant observation, as we investigated miR3653 expression in Huh-7 HCC CSC cells by enhancing STIM1 and Orai1 expression, which mimics poor cancer prognosis, instead of using parental EpCAM(-)/CD133(-) Huh-7 cancer cells." (PMID 36556285, 2022). "Analysis of the non-leukocyte (CD45-) subpopulation of TCPPHIGH cells revealed that the cancer group contained a larger percentage of cells stained with the epithelial markers panCK and EpCAM." (PMID 35976857, 2022). "These components and their mixture down-regulated EpCAM expression and inhibited the adhesion of cancer cells to human endothelial cells." (PMID 36184654, 2022). "This made it possible to perform targetedtransfection of exclusively EpCAM-overexpressing cancer cells and effectivelyinhibit the biosynthesis of Bcl-2." (PMID 35441046, 2022). "The knockdown of EphB4 and ephrinB2 on the cancer cell was confirmed by co-immunofluorescence staining between EpCAM and EphB4 or ephirnB2." (PMID 35725568, 2022). "It has been reported that various cancer-related genes (EpCAM, VIM, and NPTN, among others) increase in these immune cells." (PMID 36012405, 2022). "Decreased expression of βII-spectrin downregulated the expression of kallistatin, thereby activating Wnt/β-catenin signaling and increasing the EpCAM+ subpopulation of cancer cells." (PMID 36369033, 2022). "After 12 h, death of cancer cell (indicated as EpCAM+) was examined by PI and Annexin V uptake using flow cytometry." (PMID 35794100, 2022). "EpCAM+ CTCs and EpCAM− CTCs, each with different ploidy of chromosome 8, were effectively detected in patients with hepatobiliary malignances." (PMID 36091119, 2022). "EpCAM+ (Epithelial Cell Adhesion Molecule) cancer with symptomatic malignant ascites.Paracentesis alone or in combination with Catumaxomab.Randomised, open-label." (PMID 35020853, 2022).
cancer (continued). "The electrochemical Lab-on-a-Disc (eLoaD) platform captures cancer cells from separated plasma through anti-EpCAM antibodies immobilized on gold electrodes and quantifies them by the use of label-free electrochemical impedance." (PMID 35962400, 2022). "The expression of EpCAM is associated with cell proliferation and is prominent among CSC‐enriched populations in HCC and many other types of cancers." (PMID 35152538, 2022). "Our cell line identification method enables us to provide the real-time assessment of the heterogeneity of the rare cancer cells in given in-vitro sample, which offers rapid detections of the EpCAM+ and EpCAM− cells." (PMID 35393460, 2022). "Taking COAD as an example, it had the most BCAT1 mutations among the 32 cancers included in our study, and interestingly, BCAT1 expression was negatively relevant to the expression of an MMR gene––EPCAM." (PMID 34984849, 2022). "An epithelial cell adhesion molecule (EpCAM) is an antigen that is expressed in cancer stem cells and epithelial cells." (PMID 36559056, 2022). "Subsequently, the cancer cell‐targeting agent, biotinylated anti‐EpCAM, was bound on the biotin–BSA surface through biotin–streptavidin recognitions." (PMID 37324582, 2022). "In our current study, the primary objective was to investigate the occurrence of rare cancer cells based on the specific binding of QDAb for the EpCAM+ and EpCAM− (CD44+ and CD45 +) cell lines in-vitro based peripheral blood mimic sample co-culture models." (PMID 35393460, 2022). "EpCAM+ cancer cells would be available for screening common neoantigens expressed in cancer cells with heterogeneous characteristics." (PMID 36293034, 2022). "With more precision and accuracy, the current defined protocol successfully assessed rare cancer cell events based on the EpCAM+ and EpCAM− marker systems." (PMID 35393460, 2022). "The first BsAb approved for cancer treatment was catumaxomab, which activates endogenous T cells by connecting CD3 with epithelial cell adhesion molecule (EpCAM) on cancer cells, indicating for malignant ascites therapy." (PMID 35664074, 2022). "In this study, the number of epithelial cell adhesion molecule (EpCAM)-positive cancer cells in malignant ascites of two patients was dramatically reduced after intraperitoneal infusion of CAR NK cells." (PMID 36428748, 2022). "EpCAM has been identified as a cancer stem cell marker in solid tumors and has a significant correlation with all the characteristics of cancer stem cells, EMT, and metastasis." (PMID 35986321, 2022). "Functionalized EVs demonstrated increased accumulation in target cells expressing common cancer associated markers such as CXCR4, EGFR and EpCAM both in vitro and in vivo." (PMID 35547755, 2022). "Some more ADCs are emerging as promising EpCAM-targeting complexes for cancer treatment, evidenced by in vitro cell lines assays and in vivo animal experiments." (PMID 36369033, 2022). "Microfluidic chips with multiple arrays of microscopic posts coated with cancer-specific ABs (e.g., anti-EpCAM AB) increase the interactive surface between the putative CTCs in the bloodstream and the ABs, resulting in increased enrichment efficacy." (PMID 35056131, 2022). "Most studies have analyzed the relationship between high EpCAM expression in cancer cells and permanent proliferation signals, as well as overexpression of various targeted genes, including c-Myc and cyclins." (PMID 35986321, 2022).
cancer (continued). "Using in vitro experiments, we demonstrated that the knockdown of Smurf2 expression accelerated cell migration, promoted sphere formation, and increased the expression of EpCAM, a cancer stem cell marker." (PMID 35361871, 2022). "We also found that the cancer cells infected by BCG expressed significantly lower membrane levels of EpCAM." (PMID 35503263, 2022). "At the same time, the roles of EpCAM in cancer progression are found to be highly context-dependent and even contradictory in some cases." (PMID 36369033, 2022). "The expressions of epithelial cell adhesion molecules (EpCAM) and cytokeratins (CK) are highly dynamic in different types or stages of cancer cells, especially in those undergoing EMT, which results in the failure of CTC detection using the CellSearch system." (PMID 35387131, 2022). "On the other hand, CD8+ T cells in response to SMAD4P130L, which is homogeneously expressed in EpCAM+ cancer cells, were detected using in vitro expansion with the HLA-A*11:01 restrictive SVCVNLYH neoantigen." (PMID 36293034, 2022). "CD326 (i.e., epithelial cell adhesion molecule; EpCAM) is expressed in epithelial tissues, germ and somatic stem cells, and cancer cells." (PMID 35629138, 2022). "These molecular mechanisms further border the functions of EpCAM and complicate its role in cancer progression." (PMID 36369033, 2022). "The EINPs were designed to primarily target cancer cells overexpressing EpCAM, entering the MCF-7 cells due to receptor-mediated endocytosis and eliminating them preferentially with Na131I." (PMID 35877345, 2022). "Despite the EpCAM expression level variability detected on the surface of these cancer cell lines, the apparent binding affinities of different EpCAM-specific ICE® constructs were similar." (PMID 35225870, 2022). "In this study, the results revealed that EpCAM is highly expressed in several types of cancer, with a particularly strong correlation between high EpCAM expression and a poor prognosis in PCa patients." (PMID 35517503, 2022). "EpCAM is primarily considered an adhesion molecule but has more recently been reported to regulate cell proliferation and cancer stemness." (PMID 35892853, 2022). "For example, in metastatic lymph nodes in several cancer types, the increased expression of Esx/Elf3 correlated to an increased expression of EPCAM." (PMID 36230521, 2022). "The results of in vivo testing demonstrated that EpCAM + CD133 − cancer stem cells are more resistant to treatment using LDL nanoparticles packed with docosahexaenoic acid compared to EpCAM − CD133 − adult cancer cells." (PMID 35248080, 2022). "Cancer cells are recognized and captured by EpCAM aptamers on recognition MNs which then triggers the release of complementary strands inducing a subsequent drug release." (PMID 35216097, 2022). "FOXK1 upregulation in HCC cells led to expand the population of cancer stem cells by increasing EpCAM and ALDH1 expression levels." (PMID 35255005, 2022). "Recent studies have reported the presence of particular membrane proteins, for example, CD47, and EpCAM on the cancer cell membranes that regulate immune tolerance and the cell adhesion ability of cancer cells to avoid macrophage uptake." (PMID 36365249, 2022). "Only combination of antigens being simultaneously present on the same large EV, here AnnexinV, CD147 (Emmprin) and EpCAM were sufficient to separate patients suffering from thyroid gland and cancers." (PMID 35966579, 2022).